RNU7-147P (RNA, U7 small nuclear 147 pseudogene)
Gene: Small nuclear RNA gene on chromosome 2 (199,191,059 to 199,191,120, forward strand). Ensembl gene ENSG00000238698.
Homologues: Orthologues: chimpanzee U7 (97% identical), macaque U7 (94% identical). Paralogues in human: RNU7-28P (89% identical), RNU7-11P (87% identical), RNU7-128P (87% identical), RNU7-14P (87% identical), RNU7-7P (87% identical), RNU7-22P (85% identical), RNU7-3P (85% identical), RNU7-6P (85% identical), RNU7-13P (84% identical), RNU7-18P (84% identical), RNU7-23P (84% identical), RNU7-35P (84% identical), and 143 more.